ZSCAN26 (zinc finger and SCAN domain containing 26)
Description:
May be involved in transcriptional regulation.
Synonyms: ZNF187; SRE-ZBP; SREZBP
Tractability: PROTAC: UniProt records ubiquitination sites on it; its protein half-life has been measured.
Gene: Protein-coding gene on chromosome 6 (28,267,058 to 28,278,224, forward strand). Ensembl gene ENSG00000197062.
Subcellular location: Nucleus
Subcellular location (Human Protein Atlas): Nucleoli; Nucleoplasm
Gene Ontology:
Molecular function: protein binding; DNA-binding transcription factor activity; DNA-binding transcription factor activity, RNA polymerase II-specific; RNA polymerase II cis-regulatory region sequence-specific DNA binding
Biological process: regulation of DNA-templated transcription; regulation of transcription by RNA polymerase II
Cellular component: nucleolus; nucleoplasm; nucleus
Genetic constraint (gnomAD): Loss-of-function variants: 29 observed, 25.22 expected, observed/expected ratio (o/e) 1.15, 90% interval 0.86 to 1.57. The upper end of that interval is the gene's LOEUF score, 1.57, which puts it in group 6 of 6, group 1 being the genes least tolerant of losing a copy. Missense variants: 528 observed, 594.39 expected, observed/expected ratio (o/e) 0.89, 90% interval 0.83 to 0.95. Synonymous variants: 180 observed, 213.22 expected, observed/expected ratio (o/e) 0.84, 90% interval 0.75 to 0.95.
Homologues: Orthologues: chimpanzee ZSCAN26 (99% identical), macaque ZSCAN26 (95% identical), pig ZSCAN26 (83% identical), rabbit ZSCAN26 (80% identical), dog ZSCAN26 (78% identical), rat Zscan26 (70% identical), mouse Zscan26 (70% identical), guinea pig ZSCAN26 (69% identical). Paralogues in human: ZKSCAN8 (46% identical), ZSCAN30 (43% identical), ZKSCAN4 (43% identical), ZSCAN12 (43% identical), ZKSCAN3 (42% identical), ZNF397 (42% identical), ZKSCAN1 (42% identical), ZSCAN22 (41% identical), ZNF394 (40% identical), ZNF263 (39% identical), ZSCAN31 (39% identical), ZNF165 (39% identical), and 18 more.
Diseases named in the same sentence as ZSCAN26 in open-access papers:
ZSCAN26 is named in the same sentence as 9 diseases in open-access papers, as found by Europe PMC text mining. Sharing a sentence is not in itself a finding about the gene and the disease. The quoted sentences say what the papers report.
glioma (1 paper, 2024). A benign or malignant brain and spinal cord tumor that arises from glial cells (astrocytes, oligodendrocytes, ependymal cells). "A pleiotropic directionality test, utilizing the MR‐Egger intercept, revealed horizontal pleiotropy (p < 0.05) specifically for the ZSCAN26‐ excitatory neurons‐all glioma association." (PMID 39722126, 2024). "Summarizing the MR results presented in the heatmap, we observed that SRA1, SCDF1, SLC25A24, ZSCAN23, and ZSCAN26 were notably associated with glioma risk across at least two cell types, with consistent MR estimates, indicating potential cross‐cell effects of these genes." (PMID 39722126, 2024).
Insulin resistance (1 paper, 2025). Increased resistance towards insulin, that is, diminished effectiveness of insulin in reducing blood glucose levels. "An integrative epigenome‐wide association study has shown that CpG sites within ZSCAN26 are associated with lower insulin resistance." (PMID 40719081, 2025).
sarcoidosis (1 paper, 2025). Sarcoidosis is a multisystemic disorder of unknown cause characterized by the formation of immune granulomas in involved organs. "Among them, there were 14 genes (ABT1, BTN2A2, C2orf74, CCDC88B, FAM213A, MDH2, METTL21B, PRSS16, RP3-473L9.4, TCF19, TSFM, UBASH3A, UQCC2, ZSCAN26) associated with sarcoidosis risk consistently across these tissues." (PMID 40075078, 2025). "In addition, our TWAS pinpointed many tissue-specific sarcoidosis-associated genes and found expressions of 14 genes (ABT1, BTN2A2, C2orf74, CCDC88B, FAM213A, MDH2, METTL21B, PRSS16, RP3-473L9.4, TCF19, TSFM, UBASH3A, UQCC2, ZSCAN26) associated with sarcoidosis across all three target tissues." (PMID 40075078, 2025).
ZSCAN26 also shares sentences with these, for which no sentence is quoted: diabetes (2 papers); IgA nephropathy (1); ischemic stroke (1); kidney disease (1); schizophrenia (1); type 1 diabetes (1).